NOX4 (NADPH oxidase 4)
Diseases named in the same sentence as NOX4 in open-access papers (continued):
Sharing a sentence is not in itself a finding about the gene and the disease.
Obesity (45 papers, 2018 to 2025). Accumulation of substantial excess body fat. "Taken together, our results show that NOX4 deficiency in the liver diminished antioxidant defense to promote hepatic and systemic insulin resistance in obesity." (PMID 38060313, 2023). "MtROS was enhanced in NOX4-deleted myotubes, and IR associated with obesity and old age was exacerbated in skeletal muscle-specific NOX4 KO mice." (PMID 37892226, 2023). "Obesity was also associated with a downregulation in the gene expression of NOX-4 (p < 0.05) and with a significant increase in the mRNA levels of GSR (p < 0.01), SOD-1 (p < 0.001) and PGC-1α (p < 0.05) in gastrocnemius muscle." (PMID 36139877, 2022). "Obesity was associated with an upregulation in the gene expression of IL-1β (p < 0.05), IL-6 (p < 0.01) and NOX-4 (p < 0.05), and with a downregulation in the mRNA levels of the antioxidant enzymes GPX-3 and SOD-1 (p < 0.01 for both) in aortic tissue." (PMID 36009292, 2022). "Several studies have reported the implication of different NOXs, especially NOX2 and NOX4, in the development of insulin resistance associated with obesity." (PMID 33800461, 2021). "Mice with adipocyte-specific Nox4 deficiency were protected against obesity-induced insulin resistance." (PMID 33748199, 2021). "Although the functions of NOX4 were identified in various types of cells, the effects of NOX4 deficiency in the brain under chronic metabolic stress such as obesity or HFD are not well known." (PMID 32438638, 2020). "NOX4-derived ROS production has been implicated in endothelial dysfunction and inflammation during obesity." (PMID 32907629, 2020). "Increases in expression of two other genes commonly associated with a systemic inflammatory state and obesity, Cox2 and Nox4, were observed in IWAT tissues of F1 males from DOSS treated dams." (PMID 30728429, 2019). "The mechanism for how this occurs is unknown, but association studies in humans indicated that NOX4 mutations may be related to the development of obesity." (PMID 40985048, 2025). "Hepatocyte NOX4 deficiency promotes obesity, steatosis, and insulin resistance in mice." (PMID 38060313, 2023). "Intriguingly, oxidative stress associated with obesity may preferentially mutate MED12 via NOX4 and TGF-β3-dependent pathways." (PMID 37628676, 2023). "Renal Nox1, Nox2, and Nox4 contribute differentially to vascular oxidative stress-associated ED in obesity, suggesting a need to identify specific Nox subunits as a target, which may result in effective prevention of obesity-related CVD." (PMID 34277732, 2021). "Although NOXs, such as NOX4, have previously been shown to regulate diet-induced obesity through impairments in BAT metabolic function, a clear thermogenic mechanism has not been described." (PMID 40498837, 2025). "In the kidney, despite decreased Hsd11b2, Nox4, and Fn1 expression with obesity, histological analysis revealed extensive glomerular damage, including swelling, increased cellularity, and narrowed Bowman’s space, suggesting significant renal pathology." (PMID 40362895, 2025). "The gene expression of the pro-oxidant gene Nox4 (p < 0.001) was significantly increased by obesity in ScWAT." (PMID 39576482, 2025). "NOX4-ROS contributes to this low-grade inflammation in AT, where inflammation drives obesity-induced impairment of insulin signaling." (PMID 39188529, 2024). "Further investigation is needed to unravel the distinct role of NOX4 expression in producing the distinct phenotype between these two tissues and to define the unique role of NOX4 in determining the pathophysiology of BM and bone metabolism in obesity." (PMID 39188529, 2024). "This suggests that NOX4-ROS in AT participates in signaling cascades responsible for the early onset of insulin resistance and the inflammatory response in obesity." (PMID 39188529, 2024). "Due to its predominant expression in endothelial cells, the role of NOX4 has been studied in more detail in the vasculature of models of obesity." (PMID 37627585, 2023).
Obesity (continued). "Our research confirms for the first time that the reduction in NOX4 in adipocytes served as a molecular mechanism mediating the anti-obesity effects of DHA." (PMID 36915539, 2023). "Scientists transiently elevated adipocyte Nox4 and pentose phosphate pathway activity in mice during obesity development driven by a high-fat and high-sucrose diet to successfully prevent obesity-induced insulin resistance." (PMID 36830032, 2023). "The obesity-reducing effect of the treatment with dihydroartemisinin (a malaria medication) has also been attributed to decreased Nox4 expression and subsequent attenuated adipocyte differentiation and lipid accumulation." (PMID 37627585, 2023). "Obesity induced a significant decrease in the mRNA levels of NOX-4 (p < 0.05), GSR (p < 0.01), GPX-3 (p < 0.05), and SOD-1 (p < 0.05)." (PMID 36139877, 2022). "Supplementation with WTE prevented the obesity-induced changes in the gene expression of IL-1β, IL-6 and NOX-4 (p < 0.05 for all)." (PMID 36009292, 2022). "The consensus is that increased NOX4 contributes to or exacerbates obesity and obesity-related phenotypes, which was derived from observed increases in NOX4 in adipose tissue, muscle, and liver during overnutrition." (PMID 35601828, 2022). "NOX4 is the major NOX isoform in adipocytes and ROS production in early obesity depends on NOX4 transferring electrons from NADPH to oxygen." (PMID 35883829, 2022). "It is reasonable to assume that obesity promotes the development of DCM via NOX4 participating in the immune response and ferroptosis by activating NADPH oxidase and NLRP3 inflammasomes." (PMID 36547458, 2022). "DCE prevented the changes in the gene expression of GSR, PGC-1α and NOX-4 (p < 0.05 for all) induced by obesity and also increased the mRNA levels of GPX-3 (p < 0.05)." (PMID 36139877, 2022). "Whole-body NOX4 knock-out mice were employed to study the role of NOX4 in HFD-induced obesity, metabolic alterations, insulin resistance and liver steatosis." (PMID 35740032, 2022). "DC attenuated the reduction in the gene expression of GSR and SOD-1 (p < 0.05 for both), whereas DCE, DCT, and DCTE completely prevented the obesity-induced reduction in the mRNA levels of NOX-4, GSR, GPX-3 and SOD-1 (p < 0.05)." (PMID 36139877, 2022). "These significant observations indicate that ER-localized Nox4-induced IRE1α sulfonation results in the decay of SIRT1 as a novel mechanism behind the positive implications of GABA on obesity." (PMID 35458241, 2022). "On the other hand, elevated NOX4 levels have been observed in the adipose tissue in rodent models of obesity, as well as in humans with extreme insulin resistance." (PMID 33893069, 2021). "During obesity development, induced by a high-fat and high-sucrose diet, adipocyte Nox4 and pentose phosphate pathway activity were transiently increased in mice." (PMID 33748199, 2021). "In accordance with our results, a knockout mice model for NOX4 seemed to facilitate weight gain and obesity development." (PMID 33800461, 2021). "Taken together, these studies point toward the importance of miR-146a in directly regulating the beneficial effects of NOX4 on the endothelium during obesity." (PMID 32907629, 2020). "Diet-induced obesity in mice is accompanied by increased AT NOX-4 activity, the inhibition of which leads to decreased ROS and AT-inflammation." (PMID 31766503, 2019). "While wild type mice fed a 12-week high fat diet gained significant body weight and abdominal adiposity, NOX4 KO exacerbated the development of obesity within two weeks." (PMID 31382355, 2019). "Furthermore, NOX4 mediates the protective effects of physical activity against obesity-induced vascular dysfunction." (PMID 38790608, 2024). "Thus, steatosis in obesity was accompanied by the induction of NOX4 and the NFE2L2 antioxidant defense response in hepatocytes." (PMID 38060313, 2023).
Obesity (continued). "In addition, both DCM and obesity had a similar immune micro-environment, possibly involving NOX4, related to immune response and ferroptosis." (PMID 36547458, 2022). "NOX4-derived ROS in the development of obesity and insulin resistance." (PMID 36359402, 2022). "NOX4, CCDC80, COL1A2, HTRA1, and KLHL29 were identified as key genes by LASSO regression analysis, among which HTRA1 and KLHL29 showed a close association with immune system infiltration in DCM and obesity." (PMID 36547458, 2022). "In order to investigate whether LEO alleviated the oxidative stress induced by obesity, NOX4 mRNA levels were measured both in vivo and in vitro." (PMID 35883829, 2022). "However, studies have found that deleting NOX4 can either exacerbate or attenuate obesity and obesity-related phenotypes, depending on the model system: Liver-specific deletion/inhibition of NOX4 decreased inflammation and fibrosis." (PMID 35601828, 2022). "The role of NOX4 in obesity and overnutrition remains controversial." (PMID 35601828, 2022). "To explore in more detail the molecular mechanisms involved in renal injury in the obesity mouse model with tubular Adam17 deletion, we analyzed the gene expression of cortical NADPH oxidase 4 (Nox4) and phosphorylated Dynamin-Related Protein (pDRP1) expression as markers of oxidative stress." (PMID 34884897, 2021). "In the time course of obesity, sources of ROS in adipose tissue may change from Nox4 primarily in adipocytes at early stage, to Nox2 in macrophages at intermediate stage, and finally to mitochondria oxidative phosphorylation at later stage." (PMID 33748199, 2021). "The control of the H2O2 redox balance and/or NOX4 and AMPKα activity in white adipocytes may be a useful target for new therapies for obesity, as demonstrated in this in vivo and in vitro study." (PMID 33080438, 2020). "Our results suggest that NOX4 could be a critical gene for protecting against neuronal disorder during chronic metabolic diseases including obesity and type 2 diabetes." (PMID 32438638, 2020). "Treatment with a NOX4 inhibitor or AMPK activator rescued the propensity for obesity of CKO mice." (PMID 33080438, 2020). "While the relevance of these findings in the vasculature requires functional verification, this study indicates that miR-25 may directly target NOX4 to induce ROS production in ECs during obesity." (PMID 32907629, 2020). "•Antioxidants, NOX4 inhibitors, and AMPKα activators prevent obesity." (PMID 33080438, 2020). "Obesity increases the expression of NOX4; this ROS-generating enzyme could be responsible for the redox modification of RyR2 in obese mice." (PMID 29439404, 2018). "Thus, targeting NOX4 in obesity-induced bone fragility may be an interesting target for potential treatment in patients with metabolic bone diseases." (PMID 39188529, 2024). "Furthermore, NOX4 downregulation of skeletal muscle during aging and obesity has been shown to contribute to the development of insulin resistance and may promote oxidative stress." (PMID 37175460, 2023). "In addition, our results suggest that NOX4 could have an important role in the neuronal protection through hippocampal neurogenesis under human metabolic diseases such as obesity and type 2 diabetes." (PMID 32438638, 2020). "Our results showed that NOX4 had an elevated expression in both DCM and obesity, connecting with immune response and ferroptosis." (PMID 36547458, 2022). "The key genes, NOX4, CCDC80, COL1A2, HTRA1, and KLHL29 were significantly expressed in DCM, with KLHL29 and HTRA1 especially closely associated with the immune response, which might be markers for obesity-induced DCM and be potential avenues for exploration in immunotherapy." (PMID 36547458, 2022). "DC only attenuated the obesity-induced downregulation of NOX-4 (p < 0.05), whereas DCE also prevented the alterations in the mRNA levels of NOX-4 (p < 0.01), GSR (p < 0.05) and GPX-3 (p < 0.01)." (PMID 36139877, 2022).
Obesity (continued). "NOX4 signaling is dysregulated in obesity, contributing to insulin resistance, extracellular matrix fibrosis, and hypertrophy observed in WAT of people with obesity." (PMID 40985048, 2025). "In rWAT, two-way ANOVA revealed statistically significant increase in p22 (p < 0.001), Nox2 (p < 0.001) and Nox4 (p < 0.01) expression due to obesity but administration of QCT did not significantly affect the expression of these genes." (PMID 39576482, 2025). "To explore the effect of NOX4 abundance on hepatic pathophysiology in diet-induced obesity (DIO), we sought to delete Nox4 postnatally in hepatocytes using the Alb-Cre transgene; Nox4 was efficiently deleted in the livers and hepatocytes of Alb-Cre Nox4fl/fl mice, but not in other metabolic tissues." (PMID 38060313, 2023). "Although the mechanism by which statins downregulates NOX4 expression was not examined, our data indeed support the conception that statins protect kidney injuries during obesity independent of its property of lowering cholesterol." (PMID 35562673, 2022). "Finally, DCT attenuated the obesity induced-changes in the gene expression of NOX-1 (p < 0.05), NOX-4 (p < 0.01), and GPX-3 (p < 0.05) and DCTE the changes in NOX-1 and NOX-4 (p < 0.05 for both)." (PMID 36139877, 2022). "NOX4 is a regulator of metabolic homeostasis as the absence of NOX4-mediated ROS production results in adipose tissue hypertrophy, and sensitivity towards diet-induced hepatosteatosis and obesity." (PMID 33893069, 2021). "Manipulating NOX4 and AMPK in white adipocytes may be a therapeutic tool against obesity augmented by oxidative stress." (PMID 33080438, 2020). "CKO mice are obesity-prone, presenting elevated H2O2 and NOX4 expression in adipose tissue." (PMID 33080438, 2020). "Thus, mitochondria- and NOX4-derived ROS function in concert to drive a NFE2L2 antioxidant defense response to attenuate oxidative liver damage and progression to NASH and fibrosis in obesity." (PMID 38060313, 2023). "Therefore, NAFL, but not obesity per se, was accompanied by the increased expression of NFE2L2 targets genes, including NOX4, which encodes a ROS-producing enzyme, and NQO1, SOD2, and CAT, which encode key antioxidant defense enzymes, but these declined with more advanced disease and fibrosis." (PMID 38060313, 2023). "In summary, our study revealed that DHA exerts a therapeutic effect on obesity in an HFD-induced obese mice by inhibiting adipocyte differentiation, and that its mechanism of action may lie in its inhibitory effect on the ROS-producing enzyme NOX4 and abnormal cell-metabolism pathways." (PMID 36915539, 2023). "Our findings seemingly contrast with those of previous studies reporting that the deletion of Nox4 in hepatocytes attenuates NASH and fibrosis in mice fed diets that promote NASH and fibrosis, with or without obesity." (PMID 38060313, 2023). "Moreover, except for NOX4 expression, which trended lower, NFE2L2, NQO1, SOD2, and CAT gene expression declined in patients with obesity (BMI = 47–74) with NASH and fibrosis (NAS = 5–6; fibrosis score = 1–2) to levels evident in patients with obesity with nonsteatotic livers." (PMID 38060313, 2023).
renal fibrosis (44 papers, 2013 to 2026). A final common manifestation of a wide variety of chronic kidney diseases characterized by glomerulosclerosis and tubulointerstitial fibrosis. "The transcription factor EGR1, which is expressed in several renal cell populations, has been shown to be associated with renal fibrosis and inflammation as well as being a transcriptional activator of NOX4 in DKD." (PMID 38671844, 2024). "In db/db mice, NOX-4 is involved in molecular mechanisms underlying renal fibrosis through increased TGF-beta and fibronectin production." (PMID 30425780, 2018). "NOX4 has been implicated in the basal production of reactive oxygen species (ROS) in the kidneys, and its upregulation may promote renal oxidative stress and renal fibrosis." (PMID 30993112, 2019). "This study suggests that KM ameliorates renal fibrosis by inhibiting NOX4-mediated ferroptosis in renal tubular cells." (PMID 40766752, 2025). "NOX4 is the main source of reactive oxygen species in the kidney and plays an important role in renal fibrosis." (PMID 36661510, 2023). "At the same time, RAAS, and specifically Ang II, act as a key stimulator of NOX (such as NOX4 in the kidney), contributing to ROS-mediated damage in many pathologies including renal fibrosis with hypertension." (PMID 37353787, 2023). "Several studies have demonstrated that TGF-β increases cellular ROS through Smad-NOX4 signaling and the TGF-β1/Smad signaling pathway is an important pathogenic mechanism in cardiac, hepatic, pulmonary, and renal fibrosis." (PMID 35138513, 2022). "TGF-β1 can promote ROS production by inducing the expression of Nox4 and inhibiting the activity of antioxidants, playing dual roles in renal fibrosis." (PMID 35908070, 2022). "The C3a-stimulated increase in α-SMA expression, which is a specific marker for fibrotic myofibroblasts, was inhibited by NOX4 RNA silencing, suggesting that C3a mediates superoxide production and renal fibrosis through an NOX4-dependent pathway." (PMID 34806406, 2022). "Activation of the RhoA/ROCK signalling pathway can upregulate NOX4/ROS expression, promote renal muscle fibroblast differentiation, and aggravate renal fibrosis." (PMID 32496208, 2020). "It has been shown that HIPK2 mediates NOX4 expression in diabetic kidneys and that phosphate niclosamide mitigates renal fibrosis by inhibiting HIPK2 expression in the tubulointerstitial compartment." (PMID 32701510, 2020). "Previous studies have reported that in pathologic conditions, overexpression of Nox4 in podocytes and mesangial cells leads to renal fibrosis and chronic kidney disease through increasing cellular ROS level." (PMID 31318905, 2019). "Nox4-derived ROS participate in the pathological process of DN by reducing glucose tolerance, increasing the production of proteinuria, and promoting renal fibrosis." (PMID 31179338, 2019). "It is commonly accepted that Nox4 plays critical roles in hydrogen peroxide production during renal fibrosis." (PMID 28805491, 2017). "In order to determine the role of Nox4 in TGF-β1 mediated renal fibrosis, two strategies to inhibit Nox4 were used, namely the administration of a Nox4 inhibitor in in vitro and in vivo studies and Nox4 specific siRNA in in vitro studies." (PMID 23991195, 2013). "The effect of Nox4 inhibition on renal fibrosis in the diabetic mouse model was determined by examining extracellular matrix deposition." (PMID 23991195, 2013). "Notably, Rb1 has demonstrated efficacy in mitigating oxidative stress and inflammation in CKD models, while NADPH oxidase 4 (NOX4) knockout attenuates renal fibrosis by inhibiting fibroblast activation." (PMID 41508002, 2026). "Importantly, this effect was also seen in non-diabetic mice lacking NOX4 expression, suggesting a more substantial role of NOX5 versus NOX4 in modulating EMT pathways leading to renal fibrosis." (PMID 38671844, 2024).